ACADL (acyl-CoA dehydrogenase long chain)
Description:
Catalyzes the first of the four reactions of the mitochondrial fatty acid beta-oxidation (FAO) pathway, which consists in the proR-proR stereospecific alpha, beta-dehydrogenation of fatty acyl-CoA thioesters using the electron transfer flavoprotein (ETF) as their physiologic electron acceptor, resulting in the formation of trans-2-enoyl-CoA ((2E)-enoyl-CoA). The mitochondrial FAO pathway is the major energy-producing process in tissues and is performed through cycles of four consecutive reactions. Each FAO cycle shortens the fatty acyl-CoA by two carbons, yielding one acetyl-CoA (for the citric acid cycle), one FADH(2), and one NADH (which donate electrons to the respiratory chain for ATP production). Among the different mitochondrial acyl-CoA dehydrogenases, long-chain specific acyl-CoA dehydrogenase activity overlaps with that of ACADV and ACAD9, acting on saturated and unsaturated acyl-CoAs with 6 to 24 carbons with a preference for 8 to 18 carbons long primary chains. Can use (4Z,7Z,10Z,13Z,16Z,19Z)-docosahexaenoate as substrate in vitro (which is not primarily used for energy but mainly beta-oxidized in the peroxisomes). In addition, based on its established catalytic mechanism, and combined genetic interaction or mutant phenotype evidence, it is predicted to act also on substrates that have not been tested experimentally but are metabolized by mitochondrial FAO, including long-chain unsaturated fatty acids such as linoleate (9Z,12Z-octadecadienoate), linolenate (9Z,12Z,15Z-octadecatrienoate), and others. Plays a primary role in FAO in tissues where it is the main long-chain ACAD expressed, such as the lung, specifically in type 2 alveolar cells (responsible for surfactant production). Probably responsible for beta-oxidation of bulky substrates including branched chain fatty acyl-CoAs and sterol derivatives thanks to its enlarged substrate-binding cavity.
Synonyms: LCAD; ACAD4
Tractability: Small molecule: a structure with a bound ligand is known. PROTAC: its protein half-life has been measured.
Gene: Protein-coding gene on chromosome 2 (210,187,126 to 210,225,447, reverse strand). Ensembl gene ENSG00000115361.
Subcellular location: Mitochondrion matrix
Pathways (Reactome):
Metabolism: Beta oxidation of lauroyl-CoA to decanoyl-CoA-CoA; Beta oxidation of myristoyl-CoA to lauroyl-CoA; mitochondrial fatty acid beta-oxidation of unsaturated fatty acids
Gene Ontology:
Molecular function: long-chain fatty acyl-CoA dehydrogenase activity; protein binding; flavin adenine dinucleotide binding; acyl-CoA dehydrogenase activity; medium-chain fatty acyl-CoA dehydrogenase activity; oxidoreductase activity, acting on the CH-CH group of donors; protein homodimerization activity; very-long-chain fatty acyl-CoA dehydrogenase activity
Biological process: carnitine catabolic process; carnitine metabolic process, CoA-linked; fatty acid beta-oxidation using acyl-CoA dehydrogenase; lipid catabolic process; long-chain fatty acid catabolic process; negative regulation of fatty acid biosynthetic process; negative regulation of fatty acid oxidation; positive regulation of cold-induced thermogenesis; regulation of cholesterol metabolic process; temperature homeostasis
Cellular component: mitochondrion; cytoplasm; mitochondrial matrix; mitochondrial membrane
Genetic constraint (gnomAD): Loss-of-function variants: 41 observed, 42.14 expected, observed/expected ratio (o/e) 0.97, 90% interval 0.76 to 1.26. The upper end of that interval is the gene's LOEUF score, 1.26, which puts it in group 5 of 6, group 1 being the genes least tolerant of losing a copy. Missense variants: 440 observed, 482.41 expected, observed/expected ratio (o/e) 0.91, 90% interval 0.84 to 0.99. Synonymous variants: 145 observed, 160.23 expected, observed/expected ratio (o/e) 0.9, 90% interval 0.79 to 1.04.
Gene-disease validity (ClinGen):
ClinGen rates the evidence that ACADL causes each of these diseases.
long chain acyl-CoA dehydrogenase deficiency (autosomal recessive): Disputed.
Homologues: Orthologues: chimpanzee ACADL (99% identical), pig ACADL (89% identical), mouse Acadl (86% identical), guinea pig ACADL (85% identical), rat Acadl (85% identical), dog ACADL (81% identical), tropical clawed frog acadl (76% identical), zebrafish acadl (71% identical), Caenorhabditis elegans acdh-8 (27% identical), Caenorhabditis elegans acdh-1 (27% identical), Caenorhabditis elegans acdh-10 (27% identical), Caenorhabditis elegans acdh-2 (23% identical), and 4 more. Paralogues in human: IVD (31% identical), ACADM (30% identical), ACADS (29% identical), ACADSB (29% identical), ACAD8 (28% identical), ACADVL (28% identical), ACAD9 (27% identical), GCDH (23% identical), ACAD10 (23% identical), ACAD11 (23% identical), ACOX3 (20% identical), ACOX1 (20% identical), and 2 more.
Diseases named in the same sentence as ACADL in open-access papers:
ACADL is named in the same sentence as 51 diseases in open-access papers, as found by Europe PMC text mining. Sharing a sentence is not in itself a finding about the gene and the disease. The quoted sentences say what the papers report.
hepatocellular carcinoma (13 papers, 2019 to 2025). A malignant tumor that arises from hepatocytes. "ACADL is a mitochondrial enzyme that is frequently downregulated in hepatocellular carcinoma, and its low expression is significantly associated with poor clinical prognosis in hepatocellular carcinoma patients." (PMID 34970420, 2021). "ACADL can inhibit the proliferation of hepatocellular carcinoma tumor cells through Hippo/YAP signaling." (PMID 36177002, 2022). "Moreover, as ACADL expression was restored in hepatocellular carcinoma cells, the Hippo/YAP signaling pathway was suppressed, resulting in growth suppression and cell cycle arrest." (PMID 37965478, 2023). "ACADL restrains hepatocellular carcinoma by targeting Hippo/YAP signaling." (PMID 35356272, 2022). "Here, we found that ACADL was frequently downregulated in hepatocellular carcinoma (HCC), and its low expression was significantly correlated with poor clinical prognosis of HCC patients." (PMID 32219176, 2020). "To determine the expression status of ACADL in HCC, we queried The Cancer Genome Atlas (TCGA) hepatocellular carcinoma database for the expression variations between tumor tissues and normal liver tissues." (PMID 32219176, 2020). "For instance, ACADL functions as an oncogene and is up-regulated in ESCC, while it is down-regulated in hepatocellular carcinoma and exhibits a suppressive effect on tumor cells." (PMID 38402174, 2024). "Moreover, in hepatocellular carcinoma (HCC), the expression of ACADL was found significantly decreased in tumor tissues compared to normal liver tissues in both mRNA and protein levels, and restored ACADL expression suppressed HCC cell growth." (PMID 35844514, 2022). "However, in hepatocellular carcinoma (HCC), ACADL expression is reduced and has a suppressive effect on cancer, with lower levels of ACADL associated with poor outcomes." (PMID 38402174, 2024).
prostate carcinoma (8 papers, 2017 to 2024). A carcinoma that arises from epithelial cells of the prostate gland. "It has been reported that the expression of ACADL protein was positively associated with malignant progression in prostate cancer." (PMID 35844514, 2022). "Previously, several studies have been reported that FH is frequently mutated in renal cancer, ELOVL2 is upregulated in hepatocellular cancer, and ACADL is associated with prostate cancer progression." (PMID 29262542, 2017). "ACADL promotes prostate cancer cell growth, as well as malignant transformation, when expressed in prostate cancer tissues, with a positive correlation between malignancy and metastasis." (PMID 36936412, 2023). "Interest in ACADL in tumor biology has focused mainly on prostate cancer, breast cancer, and esophageal squamous cell carcinoma, primarily to study its influence on the occurrence, development, and treatment of tumors." (PMID 33688464, 2021). "It was reported that ACADL contributed to the progression of prostate carcinoma and enhanced the malignant phenotypes of prostate cancer cells." (PMID 32219176, 2020). "Abnormally expressed ACADL has been detected in prostate cancer and esophageal squamous cell carcinoma." (PMID 33282950, 2020). "Similarly, ACADL contributes to the progression and malignancy of prostatic carcinoma." (PMID 38402174, 2024). "Subsequent studies revealed a relationship between ACADL and tumor progression in various human cancers, such as HCC, melanoma, breast cancer, ESCC, and prostate carcinoma." (PMID 38402174, 2024).
breast carcinoma (6 papers, 2020 to 2024). "ACADL plays a significant role in the unfavorable prognosis and controls the development of breast cancer." (PMID 38660376, 2024). "In this study, using TCGA data, HSD17B7, ACADL, ME1, MAOA, and TDO2 were identified as the top five DEGs related to FA metabolism in breast cancer tissues." (PMID 36936412, 2023). "The role of ACADL in the progression and development of breast cancer has not been studied." (PMID 36936412, 2023).
cardiac hypertrophy (6 papers, 2017 to 2024). "A recent study highlighted the role of the KLF7/PFKL/ACADL axis in regulating myocardial metabolic remodeling during myocardial hypertrophy." (PMID 38347951, 2024). "Hyperacetylation of ACADL, as observed in the irradiated mitochondria in this study, is reported in different heart diseases such as cardiac hypertrophy and heart failure." (PMID 31652604, 2019). "Then, we sought to determine whether the KLF7/PFKL/ACADL axis regulates cardiac hypertrophy growth." (PMID 36810848, 2023). "Although we focused on PFKL and ACADL in the present study, it is very likely that the expression of other genes is also controlled by transcriptional programs involving KLF7 to induce cardiac hypertrophy." (PMID 36810848, 2023). "KLF7 can simultaneously activate and repress the expression of ACADL and PFKL respectively to mediate the pathological progression of cardiac hypertrophy." (PMID 36810848, 2023). "Our findings show that KLF7/PFKL/ACADL signaling has been shown to be an essential process for cardiac FAO and glycolysis, leading to cardiac hypertrophy and HF." (PMID 36810848, 2023). "A lack of ACADL resulted in the accumulation of diacylglycerol, liver insulin resistance, and myocardial hypertrophy." (PMID 34638602, 2021). "Thus, to assess whether KLF7 can trigger pathological cardiac hypertrophy by balancing the expression of PFKL and ACADL in vivo, we generated transgenic mice (TG) in a cardiac myocyte-specific manner." (PMID 36810848, 2023).
esophageal squamous cell carcinoma (5 papers, 2020 to 2024). Esophageal squamous cell carcinoma (ESCC) is a type of esophageal carcinoma (EC) that can affect any part of the esophagus, but is usually located in the upper or middle third. "Moreover, ACADL has been linked to the advancement of esophageal squamous cell carcinoma and the negative prognosis of affected individuals." (PMID 38660376, 2024). "For instance, in esophageal squamous cell carcinoma (ESCC), ACADL acts as an oncogene and its expression is negatively correlated with prognosis." (PMID 38402174, 2024).
Hypoglycemia (5 papers, 2018 to 2024). A decreased concentration of glucose in the blood. "ACADL deficiency causes hepatic and cardiac lipidosis, hypoglycemia, and impaired fatty acid oxidation in mice." (PMID 38292759, 2024). "ACADL deficiency pronounced hypoglycemia, accumulation of lipids, elevated levels of free fatty acids in the bloodstream, and impaired insulin sensitivity in the liver." (PMID 38660376, 2024). "ACADL is a key factor in multiple metabolism pathways, mice deficient the ACADL gene had severe liver and cardiac lipid deposition hypoglycemia, elevated serum free fatty acids and liver insulin resistance due to impaired oxidation of fatty acids." (PMID 36634657, 2023). "Research shows that ACADL deficiency causes cardiac lipids and hypoglycemia." (PMID 36670821, 2023). "Furthermore, ACADL has been shown to be associated with the deposition and differentiation of yak IMF, and ACADL deficiency can lead to severe hepatic and cardiac lipidosis, hypoglycemia and hepatic insulin resistance." (PMID 36670821, 2023).
Insulin resistance (5 papers, 2020 to 2024). Increased resistance towards insulin, that is, diminished effectiveness of insulin in reducing blood glucose levels. "Mice with ACADL deficiency exhibit hepatic insulin resistance caused by impaired fatty acid oxidation." (PMID 39334848, 2024). "Mitochondrial dysfunction caused by ACADL deficiency can lead to hepatic steatosis and insulin resistance." (PMID 36936412, 2023).
steatosis (4 papers, 2011 to 2022). Increased lipid within the cytoplasm of cells. "ACADL, which encodes a dehydrogenase enzyme that catalyzes the initial step in each cycle of mitochondrial fatty acid β-oxidation, was also overexpressed in the group LC12.75; this effect was also described after the consumption of tomato juice in rats with steatosis." (PMID 33114278, 2020). "Furthermore, treatment with a PPARα agonist improved steatosis in fatty liver Shionogi mice and reduced hepatic triglyceride level by inducing expression of several genes involved in the turnover of fatty acids, e.g., ACADL." (PMID 21339799, 2011).
diabetes (3 papers, 2022 to 2024). "Initially identified for its role in lipid and energy metabolism, ACADL has been implicated in various metabolic disorders, including central obesity, cardiovascular disease, diabetes, and nonketotic hypoglycemia." (PMID 38402174, 2024). "The higher levels of ACADL seen in STZ-diabetic mice per se likely reflect increased lipid transport and β-oxidation because of chronic uncontrolled diabetes." (PMID 37015997, 2023). "ACADL is widely involved in energy and phospholipid metabolism, and its abnormal expression has been detected in various conditions, including cardiovascular disease, central obesity, nonketotic hyperglycemia, and diabetes." (PMID 38402174, 2024).
Hepatic steatosis (3 papers, 2017 to 2023). Steatosis is a term used to denote lipid accumulation within hepatocytes. "In turn, a recent study using a mouse model demonstrated that fructose-mediated fatty liver disease is likely mediated by impairment of fatty acid oxidation due to deacetylation of Acyl-CoA dehydrogenase, long chain (ACADL) and carnitine palmitoyl- transferase 1α (CPT1α)." (PMID 32670573, 2020).
lung carcinoma (3 papers, 2020 to 2021). "CPT1B and ACADL were the most important in the diagnosis of lung cancer in logistic regression models." (PMID 34970420, 2021). "At the protein level, ALDH18A1 and CPT1B were significantly upregulated, and ACADL and PPARG were slightly underexpressed, in the lung cancer group compared to the control group, which were consistent with the results of their corresponding mRNA expressions." (PMID 34970420, 2021). "ACADL, CD36, LPL, and MMP1 were the signature genes in the PPAR pathway that were identified to be shared among IPF and lung cancer." (PMID 33046043, 2020). "Four differentially expressed MMRGs (ACADL, ALDH18A1, CPT1B, and PPARG) established a logistic regression model, which could effectively diagnose lung cancer." (PMID 34970420, 2021). "Treatment with PPAR/PGC-1α complex agonists in mouse models of melanoma and lung cancer promoted FA catabolism, correlating with improved CD8+ T-cell effector function and increased acyl-CoA dehydrogenase long chain (LCAD) expression, an enzyme involved in FAO." (PMID 34944851, 2021).
dyslipidemia (2 papers, 2011 to 2016). "PPARα agonists used to treat dyslipidemia have been shown to moderately induce the expression of ACADL and ECHS1 in rat liver, and in rat heart muscle PPARα agonists increase the expression of ECHS1 and reduce the expression of HADHA/B." (PMID 21339799, 2011).
gastric cancer (2 papers, 2015 to 2024). A primary or metastatic malignant neoplasm involving the stomach. "Some nonsynonymous mutations caused low levels of gene activity with down-regulation of mRNA expression (ZNF208, CRNN, IREB2 and ACADL), which may be crucial tumor suppressor genes for gastric cancer and may contribute to the extensive dissemination of cancer cells in abdominal cavity." (PMID 26330360, 2015).
meningioma (2 papers, 2023). A generally slow growing tumor attached to the dura mater. "In accordance with the reported frequent inactivation of tumor suppressor genes in MG4 and MG3, atypical meningiomas with MCM2 or ACADL immunostaining had higher mitotic counts, reflecting a high proliferative activity." (PMID 37014425, 2023). "Recently, the immunohistochemistry (IHC) markers S100B, SCGN, ACADL and MCM2 have been shown to be associated with underlying biological subtypes of meningioma (MG1-MG4)." (PMID 36685704, 2023). "Twelve meningiomas were classified as IHC-G1 (MCM2-/ACADL-)." (PMID 37014425, 2023). "In this study, we analyzed for the first time whether ACADL and MCM2 immunostainings, used as surrogates to determine molecular groups MG3 and MG4, could predict the recurrence risk of atypical meningiomas and to identify cases which could benefit from adjuvant treatments in clinical practice." (PMID 37014425, 2023). "In conclusion, this is the first study to show that immunostainings for MCM2 and ACADL may be useful for identifying atypical meningiomas characterized by higher genomic instability, CDKN2A HeDe, higher integrated molecular grade, recurrence risk, and shorter RFS." (PMID 37014425, 2023). "In total, 244 patients with meningiomas with tissue in TMAs were included and the IHC markers S100B, SCGN, ACADL and MCM2 were analyzed." (PMID 36685704, 2023). "Finally, 34 meningiomas, showing MCM2 immunostaining in 20–90% cells, were IHC-G3 (MCM2 +); 17 of these cases had concurrent ACADL immunostaining in 10–80% tumor cells." (PMID 37014425, 2023). "All four meningiomas lacking MCM2 and ACADL immunostaining (IHC-G1) were classified as integrated grade 1; all three meningiomas in IHC-G2 (ACADL + /MCM2-) were classified as integrated grade 3, whereas 5/8 tumors in IHC-G3 (MCM2 +) were classified as integrated grade 2 or 3 (P = 0.0166)." (PMID 37014425, 2023). "MG3 and MG4 may be recognized using immunohistochemistry against ACADL and MCM2, but whether these immunostainings may be useful to identify meningiomas with a higher recurrence risk has not been investigated." (PMID 37014425, 2023). "In this study, we investigated whether the immuno-expression of ACADL and MCM2, used as surrogates of molecular groups MGM3 and MGM4, is associated with reduced RFS or with clinical, pathological and genetic features in a cohort of 55 atypical meningiomas treated with surgery and no radiotherapy." (PMID 37014425, 2023).
Obesity (2 papers, 2020). Accumulation of substantial excess body fat. "ACADL is involved in catalyzing the final reaction of triglyceride synthesis and its overexpression is frequently observed in patients with obesity and type 2 diabetes." (PMID 33255236, 2020).
pancreatic cancer (2 papers, 2023 to 2024). "The co-expressed genes of the NT5DC family, including UGT2B7, MT1G, ACADL, MT1H, and others, were found to be associated with pancreatic cancer in previous studies 37-40." (PMID 37576396, 2023).
aortic stenosis (1 paper, 2023). Aortic valve stenosis is a aortic valve disease caused by the incomplete opening of the aortic valve. "ACADL, involved with the oxidation of unsaturated FA was markedly diminished in aortic stenosis rats regardless of exercise." (PMID 37654004, 2023).
Atypical Meningioma (1 paper, 2023). A WHO grade II meningioma characterized by the presence of an increased mitotic activity or at least three of the following morphologic features: small cells, high cellularity, prominent nucleoli, lack of architectural pattern, and necrosis. "We studied 55 primary atypical meningiomas, treated with gross total resection and no adjuvant therapies, to assess whether ACADL and MCM2 immuno-expression may identify patients at higher recurrence risk, thus requiring adjuvant treatments." (PMID 37014425, 2023).